HEATR4 (HEAT repeat containing 4)
Synonyms: MGC48595
Tractability: No criterion of Open Targets' tractability assessment is met for any kind of drug.
Gene: Protein-coding gene on chromosome 14 (73,478,484 to 73,558,947, reverse strand). Ensembl gene ENSG00000187105.
Subcellular location (Human Protein Atlas): Vesicles
Gene Ontology:
Molecular function: oxidoreductase activity
Genetic constraint (gnomAD): Loss-of-function variants: 84 observed, 104.77 expected, observed/expected ratio (o/e) 0.8, 90% interval 0.67 to 0.96. The upper end of that interval is the gene's LOEUF score, 0.96, which puts it in group 4 of 6, group 1 being the genes least tolerant of losing a copy. Missense variants: 1,107 observed, 1,262.8 expected, observed/expected ratio (o/e) 0.88, 90% interval 0.83 to 0.92. Synonymous variants: 430 observed, 474.18 expected, observed/expected ratio (o/e) 0.91, 90% interval 0.84 to 0.98.
Homologues: Orthologues: chimpanzee HEATR4 (99% identical), dog HEATR4 (75% identical), rabbit HEATR4 (73% identical), guinea pig HEATR4 (67% identical), rat Heatr4 (63% identical), mouse Heatr4 (59% identical), tropical clawed frog heatr4 (27% identical), zebrafish heatr4 (20% identical).
Diseases named in the same sentence as HEATR4 in open-access papers:
HEATR4 is named in the same sentence as 2 diseases in open-access papers, as found by Europe PMC text mining. Sharing a sentence is not in itself a finding about the gene and the disease.
HEATR4 shares sentences with these, for which no sentence is quoted: cancer (2 papers); neurodegenerative disease (1).